CD4 (CD4 molecule)
Diseases named in the same sentence as CD4 in open-access papers (continued):
Sharing a sentence is not in itself a finding about the gene and the disease.
lymphopenia (continued). "Lymphopenia is common in respiratory viral infections In Covid-19, while the lymphopenia is consistent in the CD4+ T cell subtype across reports, the severity of lymphopenia in the CD8+ subtype varies." (PMID 34777353, 2021). "Lymphopenia (total lymphocytes count <1500/mm3) was present in 48.7% patients, and CD4 median count was 701/mm3 (IQR: 507; 913)." (PMID 34063894, 2021). "We confirmed previous observations demonstrating that TB-IRIS individuals display pronounced CD4+ lymphopenia prior to ART initiation." (PMID 34691079, 2021). "Pre-operative lymphopenia, mainly due to CD4+ T cells exhaustion by apoptosis, correlates with poor prognosis in AAD patients undergoing surgery." (PMID 34869652, 2021). "Once inside the cell, it replicates rapidly and causes a systemic proinflammatory response with increased cytokine levels, leukocytosis, lymphopenia (in CD4+ and CD8+ T cells) and decreased interferon-α (IFNα) expression in CD4+ T cells." (PMID 34566657, 2021). "In some patients, lymphopenia has been reported to affect CD4+ and CD8+ T cells, and other lymphocytes, whereas many data suggest that SARS–CoV–2 infection has a preferential impact on CD8+ T cells." (PMID 34659245, 2021). "One patient (P7) with histoplasmosis and BCG-osis also had CD4 lymphopenia and portal vein thrombosis." (PMID 33732252, 2021). "Patients with lymphopenia show a remarkably low concentration of CD4+T, CD8+T, NK, β-cells, and lymphocyte ratio." (PMID 34066983, 2021). "Determining lymphocyte immunophenotype for idiopathic CD4 + lymphopenia in CGD with C. violaceum infection has added value for its association with mortality." (PMID 34001231, 2021). "Here, we consolidate previous reports on the partial normalization of naïve CD4+ lymphopenia and T cell immune activation and the apparent irreversibility of monocyte activation following DAA therapy in HCV infected and HCV/HIV co-infected individuals." (PMID 35062255, 2021). "Significant lymphopenia was predicted to occur following infection with C07 wherein levels of CD4 T cells and several B cell subsets decreased with infection." (PMID 34484156, 2021). "Many large retrospective cohort studies have shown that a low CD4+ T cell count is a risk factor for death in HIV-positive patients infected with PCP, and lymphopenia is a poor prognostic factor in HIV-negative patients with PCP infection." (PMID 33985440, 2021). "These are the presence of type II cryoglobulins, rheumatoid factor, and low levels of complement C4 fraction in the serum, as well as the finding of leukopenia, neutropenia and lymphopenia, particularly CD4 lymphopenia, in the peripheral blood." (PMID 34164418, 2021). "A lower ratio of circulating lymphocytes to monocytes (LMR) predicts severe and extremely severe COVID-19 as the clearance of the virus is delayed due to lymphopenia and also a decrease in CD4+ T cells." (PMID 33585111, 2021). "There is progressive lymphopenia with CD4 + T-cell attrition in the aging immune system, and reduced regulatory T-cell activity that contribute to homeostatic proliferation of lymphocytes with autoimmune tendency and unnecessary inflammatory responses." (PMID 34906189, 2021). "The lymphopenia that has been observed in COVID-19 patients mostly reflects lower levels of CD4+ T cells and CD8+ T cells that correlate with increased disease severity." (PMID 33498725, 2021). "Altered Treg homeostasis in response to the homeostatic pressure under prolonged CD4 lymphopenia resulted in the selective peripheral depletion of Tregs and the subsequent development of chronic GVHD." (PMID 34526990, 2021). "As for the immune regulation of CD, lymphopenia, reduced CD4+ T cell count, and a reduced ratio of CD4+/CD8+ T cells have been reported in CD patients." (PMID 34867792, 2021). "A transient treatment (for 5 weeks) of anti-CD4 started 7 days after CTXpre, when the induced lymphopenia began to recover." (PMID 34493727, 2021).
lymphopenia (continued). "In MHCII-D patients, lack of MHCII molecules expression on the cell surface results in severe CD4+ T-cell lymphopenia and impaired antigen-specific cellular and humoral immune responses." (PMID 34211466, 2021). "Alpinetin ameliorated lymphopenia and the apoptosis of CD4+ T and CD8+ T lymphocytes in the spleen of PICS mice." (PMID 34285925, 2021). "CD4 + lymphopenia was seen in 36.4% of the cases, with low CD3 + and CD8 + lymphocyte counts observed in 6.7% and 18.2% of CGD patients, respectively." (PMID 34001231, 2021). "In November 2017, fingolimod was discontinued due to sustained lymphopenia and low CD4+ T cell count (≤20 cells/ul)." (PMID 33530945, 2021). "The main risk factor for developing co-infection with Pneumocystis was HIV infection with low CD4+ count, followed by immunosuppressive treatments, lymphopenia, and autoimmune disease (anti-melanoma differentiation-associated gene 5 juvenile dermatomyositis)." (PMID 34356935, 2021). "While patients with mild or moderate symptoms had an increased frequency of circulating Tfh CD4+ T cells and germinal centre B cells, in patients with severe disease there was a profound reduction of circulating CD4+ T cells and B cell lymphopenia." (PMID 34696342, 2021). "Phenotype identification has the potential to guide therapy as has been previously shown in successful treatment of patients with sarcoidosis and CD4+ T-cell lymphopenia with the TNF-α antagonist, infliximab." (PMID 33718397, 2021). "It causes generalized lymphopenia, mainly of the major circulating T lymphocytes (CD3+, CD4+ and CD8+), similarly to an immune reset, followed by immune reconstitution." (PMID 34358189, 2021). "Our patients currently present milder clinical phenotypes with hypogammaglobulinemia, moderate lymphopenia, and reduced CD4+T cells." (PMID 35003082, 2021). "In the prior studies, the overwhelming expansion of CD4 positive Tem was found in the state of lymphopenia." (PMID 34993135, 2021). "By contrast, a full restoration of CD4+ lymphopenia was slower, as CD4 cell count remains lower than in controls three months after the onset of disease, although a rapid and significant recovery was observed since the third week." (PMID 34630382, 2021). "Severe lymphopenia is also linked to the higher mortality—patients with total T cell, CD8+ T cells and CD4+ T cell counts lower than 800/μL, 300/μL and 400/μL, respectively, were more likely to die." (PMID 34588946, 2021). "In peripheral blood, lymphopenia is observed with substantially reduced CD4+ and CD8+ cell counts; however, these lymphocytes are activated, with an increase in the Th17 cell population." (PMID 34315546, 2021). "Her immunological workup revealed persistent lymphopenia and low CD4 + T cell count along with elevated levels of CD19 +, CD20 +, CD16 +, and CD56 + cells." (PMID 34872585, 2021). "On T-helper lymphocytes, CXCR4 under-expression seems to be a central phenomenon in the idiopathic CD4 lymphopenia, but the infectious profiles are quite different." (PMID 34906163, 2021). "Low naïve CD4+ and CD8+ T cells (lymphopenia) and CD4+ T cells with Th17 and Th22 phenotypes represent impaired adaptive immunity and a pro-inflammatory phenotype." (PMID 34192269, 2021). "An interesting facet of our lymphocyte subset analysis revealed that all of the 4 (38%) of CGD with CD4 lymphopenia ended in a demise with C. violaceum infection." (PMID 34001231, 2021). "Critical COVID‐19 patients have various dysregulation in their immune system response, such as lymphopenia, cytokine storm, and increased frequency of exhausted CD4+ and CD8+ lymphocytes." (PMID 34499819, 2021). "The basic lymphocyte profiling showed mild CD4+ T cell lymphopenia with adequate numbers of B and NK cells." (PMID 34908525, 2021).
lymphopenia (continued). "This would provide the molecular explanation of the evidence that A‐T patients (as well as Atm−/− mice) show a reduced number of CD4‐single positive (CD4+) cells (Nissenkorn & Ben‐Zeev, 2015), which, strikingly, exactly phenocopies Gsnor−/− mice lymphopenia." (PMID 33245190, 2021). "In our cohort, we observed lymphopenia as expected in these very severe patients and more pronounced reduction over time in CD4+ T and NK cells, limiting our observation to two weeks." (PMID 34436366, 2021). "In November 2017, she had sustained lymphopenia for 1 year with an absolute CD4+ T cell count of 33 cell/ul (normal range 490–1740 cells/ul)." (PMID 33530945, 2021). "Other well-recognised conditions, which do not have a genetic explanation at this time, include Good’s syndrome and CD4 lymphopenia." (PMID 34367167, 2021). "Previous studies in metastatic breast cancer have shown inferior patient outcomes in patients with general or specific (CD4+) lymphopenia, however data on baseline blood count impact on early TNBC response to therapy and outcome are still scarce." (PMID 34367964, 2021). "Lymphopenia was shown to affect both peripheral CD4 and CD8 T lymphocytes, considerably reducing their absolute number while their condition was rather hyperactivated, as evidenced by the increase in the expression of HLA-DR." (PMID 34036411, 2021). "Severe patients had a profound lymphopenia during acute infection, with a reduction in CD4+, CD8+, B and NK cells." (PMID 34962970, 2021). "The naïve CD4+ lymphopenia observed during ageing has been attributed to progressive thymic involution and lifetime exposure to pathogens." (PMID 35062255, 2021). "The CD4+ lymphocytopenia was more prevalent in the severe cases than in the mild cases (38 vs. 29%)." (PMID 33937149, 2021). "The mechanisms underpinning naïve CD4+ lymphopenia and chronic immune activation during chronic HCV infection, in the setting of ageing and HIV co-infection, are incompletely understood." (PMID 35062255, 2021). "Flow cytometry analyses showed that lymphopenia was due to decreased CD4+ and CD8+ T cells in the blood, B cell population being unchanged." (PMID 33439360, 2021). "The peripheral T cell compartment of Eedfl/fl::β5tCre mice demonstrated a T cell lymphopenia, equally affecting CD4 and CD8 T cells." (PMID 34168132, 2021). "It modulates S1P1 receptors blocking the egress of activated lymphocytes from lymph nodes with resultant lymphopenia, predominantly affecting CD4+ T cells." (PMID 33530945, 2021). "Collectively, increased inflammatory cytokines, T lymphopenia, especially CD4 T cells (CD3+CD4+, abbreviated as CD4+) and CD8 T cells (CD3+CD8+, abbreviated as CD8+), decreased C3 and C4, were more pronounced in the deceased patients." (PMID 33664741, 2021). "She had lymphopenia and an inverted CD4/CD8 ratio before therapy, and her serum immunoglobulin G concentration was slightly higher than the normal range." (PMID 33731004, 2021). "PML arising post‐CAR‐T is likely to be a cumulative effect of multiple immunosuppressive insults, including lymphodepletion with fludarabine, corticosteroids for CAR‐T immunotoxicity, post‐CAR CD4+ lymphopenia, and B‐cell aplasia/hypogammaglobulinaemia." (PMID 35845220, 2021). "Fingolimod was discontinued in February 2018 due to lymphopenia and low CD4+ T cell count (< 20 cells/uL)." (PMID 33530945, 2021). "Persistent CD4+ lymphopenia has been related to atherosclerosis and an increase in morbidity and mortality in patients with KT." (PMID 34646838, 2021). "Lymphopenia involving in CD4+ and CD8+ T cells, B cells, and NK cells was observed in C57BL/6 mice infected with FMDV." (PMID 34960627, 2021). "All the CGD patients with C. violaceum infection in this patient series displayed CD4 + (T helper) lymphopenia." (PMID 34001231, 2021).
lymphopenia (continued). "We observed that patients with total, CD3, and CD4 lymphopenia were more likely to have higher saliva viral load on admission, but not NPS viral load on admission, when comparing with those without lymphopenia." (PMID 33467982, 2021). "During the preclinical phase of the disease, K/BxN mice exhibit CD4+ T-cell lymphopenia, which is followed by a compensatory proliferation of these cells during the early clinical phase." (PMID 33923792, 2021). "Patients with GBM also present to the clinic with lymphopenia and have significantly reduced CD4+ T cell counts; however, the fraction of CD4+ cells which are regulatory T cells (T regs) is increased in GBM patients." (PMID 32316096, 2020). "Blood biological examination showed a CRP level that returned to normal (< 5 mg/l) with profound lymphopenia of 240/mm3 [17 CD4/mm3 (7%) and 32 CD8 /mm3 (14%), flow cytometry BD FACS Canto II]." (PMID 32228484, 2020). "In humans, a marked lymphopenia with reduced memory CD4+ and CD8+ T cells in the periphery is a major feature of SAVI syndrome." (PMID 33335532, 2020). "Together these data show that proliferation induced by lymphopenia is intrinsically regulated by PTPN22 protein in both CD4 and CD8 T cells." (PMID 32047502, 2020). "Of note, all subsets seem to be differentially affected: the lymphopenia is more sustained for the CD4+ proportionally to the CD8+ compartment; B cells recover faster during hospitalization whereas NK cells are mobilized at early timepoints post-fracture." (PMID 33072114, 2020). "Most, although not all, patients who are hospitalized seem to mount both CD8+ and CD4+ T cell responses, and evidence points to possible suboptimal (lymphopenia), excessive or otherwise inappropriate T cell responses associated with severe disease." (PMID 33072707, 2020). "The diarrhea resolved within 4 days, and the lymphopenia rised to 480/mm3 lymphocytes [102/mm3 CD4 (28%) and 56/mm3 CD8 (15%)]." (PMID 32228484, 2020). "Immunophenotyping of the peripheral blood mononuclear cells (PBMCs) revealed that both patients had significant T-cell lymphopenia characterized by low naïve CD4+ T-cell (CD4+CD45RA+) and CD8+ T-cell (CD8+CD45RA+) counts." (PMID 33203071, 2020). "The most common grade 3/4 treatment related adverse events (AEs) were lymphopenia (58%), decreased CD4 count (17%), and thrombocytopenia (17%)." (PMID 32642720, 2020). "Lymphopenia affected all major lymphocyte subpopulations, such as NK cells, B cells, and T cells, including CD4+ and CD8+ T cells and Tregs." (PMID 32937615, 2020). "These septic patients presented with signs of immunosuppression including decreased mHLA-DR and CD4+ T lymphopenia compared with reference values from the lab." (PMID 33613540, 2020). "Immunological characterization revealed that all patients exhibited significant hypogammaglobulinemia and CD4+ T cell lymphopenia." (PMID 31947836, 2020). "The mean viral load of HIV-1 was higher and mean CD4 T lymphocytopenia was lower in seropositive patients for HSV-2 compared to those seronegative for HSV-2 with a statistically significant difference." (PMID 32846938, 2020). "Autologous stem cell transplant remains a backbone of MM treatment in medically fit patients, but our findings suggest that ASCT and lymphopenia-inducing therapies in MM have a largely irrecoverable effect on the CD4+ T cell population." (PMID 33013907, 2020). "Lymphopenia was evident in all naive, effector, and memory subsets of CD4+ and CD8+ T cells, but fell short of statistical significance in the naive and effector CD8+ T cell subsets." (PMID 33267869, 2020). "With respect to a possible role of T-lymphocytes, particularly in HIV-positive patients, CD4-lymphopenia was found to correlate with increased seroprevalence of anti HEV IgG." (PMID 31947836, 2020). "One is an overproduction of pro-inflammatory cytokines by monocytes, and the other is a dysregulation of lymphocytes characterized by CD4 lymphopenia and subsequently B cell lymphopenia." (PMID 33182268, 2020).
lymphopenia (continued). "Such increase was negatively correlated with CD4+ T cell lymphopenia and positively with increased IL-10 production by monocytes." (PMID 33613540, 2020). "In P5 and P6, at the time of LPD diagnosis, immunological evaluation also revealed lymphopenia, predominantly involving the CD4 population." (PMID 32192142, 2020). "The most common findings were, similar to our results, increase in neutrophil–lymphocyte ratio and T lymphopenia, with a decrease in CD4+ T cells and subsequent damage to T lymphocytes." (PMID 32668763, 2020). "The immunological profile is characterized by the reduction of CD4+ and CD8+ T-lymphocytes (lymphopenia), decreased level of CD4+cell expression of INF-γ and increased cytokines Interleukin-6 (IL6), IL-10 and tumor necrosis factor-alpha (TNFα)." (PMID 32974295, 2020). "More than 80% of the patients exhibited lymphopenia, especially for CD4+ and CD8+ T lymphocytes (91.3%), which confirmed the previous study that SARS-CoV-2 infection damaged the immune system." (PMID 32974109, 2020). "An increase in cortisol has been shown to induce apoptosis, which in turn leads to lymphopenia and even inversion of the CD4 + /CD8 + T lymphocyte ratio." (PMID 33256605, 2020). "Both HIV-1 and SARS-CoV-2 have distinct virological characteristics while sharing CD4+ T cell lymphopenia." (PMID 33384690, 2020). "In keeping with clinical human lymphodepletion regimes, we induced severe lymphopenia by treating mice with monoclonal anti-CD4 and anti-CD8 depleting antibodies and monitored the reconstitution of the T cell pool." (PMID 32047502, 2020). "Phenotypic analysis of the T cells showed increased frequency of CD44+ and significantly higher expression of Tbet and IFNγ in PTPN22 KO CD4 T cells after they underwent lymphopenia induced proliferation." (PMID 32047502, 2020). "A clinical trial of IL-7 in patients with sepsis showed that IL-7 was well tolerated, reversed sepsis-induced lymphopenia, and increased CD4+ and CD8+ T cells by 2- to 3-fold." (PMID 32687484, 2020). "In this review, we critically assessed the possible mechanisms and the potential influence of CD4+ T cell lymphopenia in acute and chronic viral infections." (PMID 33384690, 2020). "In time, there is gradual expansion in CD4+ populations, but in dTg mice lymphopenia persists to P60 (∼20% cells in dTg vs. ∼45% in 3A9 mice; end of observation)." (PMID 33013877, 2020). "No treatment-related deaths were reported; however, major grade 3/4 toxicities included lymphopenia (97%), CD4 lymphopenia (91%), neutropenia (86%), and leukopenia (83%)." (PMID 32183871, 2020). "Fewer platelets, CD3 or CD4 counts, lower complement C3 level, lymphopenia, and elevated APTT, IL-6 or IL-10 also were related to the progression from oneset to death (all P < 0.05)." (PMID 32903644, 2020). "Lymphopenia affected mainly the populations of CD4 T lymphocytes, with a reduction in absolute numbers of the subpopulations Th1, Th2, Th17, Th1/Th17, Th22, TFH cells, and Tregs, highlighting an approximate 10% reduction in the proportion of Th1 cells." (PMID 33324414, 2020). "These were accompanied by lymphopenia, hypokalemia, hypoalbuminemia, a decrease in either CD4+ T cells or lymphocyte count, and coagulation disorders, which were closely related to poor prognosis." (PMID 33232277, 2020). "Nevertheless, CD4 T cell lymphopenia carries a low predictive value suggesting the need for a more precise diagnosis tool." (PMID 32903778, 2020). "Of note, while hypogammaglobulinemia is an expected and known adverse event following RTX treatment, it has been reported that RTX treatment can induce CD4-lymphopenia." (PMID 31947836, 2020). "The HSCT was able to correct T-cell lymphopenia by expansion of naïve and memory CD4+ T-cells, CD19+ and CD8+, moreover, there was an increase of IgA and IgG2 to normal levels." (PMID 33142696, 2020).